SIRT1 (sirtuin 1)
Diseases named in the same sentence as SIRT1 in open-access papers (continued):
Sharing a sentence is not in itself a finding about the gene and the disease.
tumor (continued). "Among the seven SIRTs, SIRT1, SIRT3, and SIRT6 can be used as tumor suppressors in KIRC." (PMID 34194607, 2021). "Moreover, LAN‐mediated circadian rhythm disorder downregulated the expression of Ces1 and Sirt1, upregulated the expression of Dnmt1, while MLT supplementation eliminated the effects in the mouse tumor tissues." (PMID 34185414, 2021). "The expression of SIRT1 did not significantly correlate with a higher FNCLCC tumor grading (G2 vs. G3, p = 0.115)." (PMID 34638362, 2021). "Since CD38 could consume NAD+, NAD+ would be elevated by CD38 knock-out and then might stimulate SIRT1 and PARP1 to induce T cell differentiation into Th1 subsets for enhancing the anti-tumor effects." (PMID 34226519, 2021). "Cells stably expressing SIRT1 had markedly increased tumor-initiating capacity, with no tumors observed after the introduction of 50 cells from the control vector group." (PMID 34163012, 2021). "Interestingly, in contrast to the tumor-promoting effect of MSCs described previously, MSCs that over-express Sirtuin 1 (MSC-Sirt1) can inhibit prostate cancer tumor growth by inducing IFN-γ production in vivo." (PMID 34149687, 2021). "Studies showed that SIRT1 and SIRT2 might be anticipated to assist tumor triggering, growth, and drug resistance." (PMID 33705642, 2021). "Therefore, the dual role of (promotor or suppressor) SIRT1 and also SIRT2 in modulating the tumor, makes them very attractive." (PMID 33705642, 2021). "Significantly higher levels of SIRT1 expression were observed in hypoxic peri-necrotic tumor regions, as compared to non-hypoxic or less hypoxic-appearing surrounding tumor regions." (PMID 32118205, 2020). "Moreover, we collected twenty pairs of tumor and normal liver tissues from HCC male patients, and found that expression levels of SIRT1 (p = 0.002), SIRT2 (p = 0.01), and SIRT4 (p = 0.045) were significantly up-regulated in tumor tissues." (PMID 33093847, 2020). "SIRT1, Ki-67, and PRDM1 mRNA levels were also elevated in CRC tumor tissues; these markers could contribute to CRC by promoting tumorigenesis, and inducing T cell exhaustion and functional impairment via indirect mechanisms." (PMID 32393998, 2020). "In addition, SIRT1 knockdown accelerates tumor xenograft formation by HCT116 cells, whereas SIRT1 overexpression suppresses tumor formation." (PMID 32636443, 2020). "Particularly it was seen to play a key role in the apoptotic signaling of the tumor cell through direct stimulation of caspases cascade and the inhibition of the anti-apoptotic pathways such as PTEN/PI3K/AKT, Sirt-1, AMPK/YAP, NF-κB and STAT3 that contribute to tumor cell immortality." (PMID 32331450, 2020). "Cox regression was utilised to estimate hazard ratios (HRs) for MSI and CIMP positive and negative tumours by SIRT1 genotypes." (PMID 32098999, 2020). "In vivo evidence from mouse xenografts injected with transformed cells with or without EX-527 treatment revealed that SIRT1 inhibition counteracted the effects of SIRT4 decline on tumor growth." (PMID 32863939, 2020). "Levels of TIM-3, CTLA-4, TIGIT, TOX, TOX2, and SIRT1 genes in tumor tissue were significantly higher than that of the circulation; their expressions within the TME could be induced by tumor-mediated immunosuppression." (PMID 32393998, 2020). "They aimed to detect the presence or absence of SIRT1 overexpression and its clinical significance in patients with HCC and found a statistically significant overexpression of SIRT1 in HCC tumor tissues compared with adjacent nontumor tissues." (PMID 32607257, 2020). "Even though SIRT1 has been found as a potential target of miRNA-138 in macrophages, smooth muscle cells, endothelial cells, and tumor cells, no data has been published in PCa concerning miR-138 and SIRT1 expression." (PMID 32431616, 2020).
tumor (continued). "We tested this hypothesis by studying the expression of total collagen, fibronectin, Ubc9, SIRT1, β-catenin in BRCA1 mutant TNBC cells and tumor sample derived from patient with dense breasts using immunofluorescence, immunohistochemistry, and collagen assay." (PMID 33860286, 2019). "SIRT1 is an extensively explored class III histone deacetylase and has been proven to be a trigger or brake in carcinogenesis depending on the cellular context and tumor type." (PMID 31068761, 2019). "SIRT1 is expressed at very low levels in normal liver, but it is overexpressed in HCC cell lines and in a subset of HCC, where its expression correlates with tumor stage." (PMID 31060333, 2019). "By contrast, hsa_circ_0076248 and SIRT1 showed much higher expression in tumor tissues than nontumor tissues." (PMID 30506951, 2019). "In higher stress conditions (lacking tumor suppressors and mitotic checkpoints), SIRT1 can promote tumor formation and cancerous cell growth." (PMID 31683808, 2019). "When tumor cells were treated by 200 nM SRT1720, cell migration and invasion were significantly reduced (p < 0.001), and these effects were recapitulated by the overexpression of SIRT1." (PMID 31068761, 2019). "In contrast, most studies in transgenic models support a tumor-suppressing role of SIRT1 as no increased tumor formation has been documented so far." (PMID 30038266, 2018). "Pathway analysis suggests that miR-217 could be a potential oncogenic miRNA that negatively regulates the SIRT1, SMAD7, ROBO1, and FOXO3 genes, which are involved in tumor progression by diverse mechanisms." (PMID 30195786, 2018). "They demonstrated that SIRT1 and GPER promote tumor growth both in vitro and in vivo." (PMID 30380732, 2018). "Taken together, these results suggest that Comp 5 inhibits tumor growth by SIRT1-mediated autophagy in vivo without obvious toxicity." (PMID 29991742, 2018). "miR-34a, a putative tumor suppressor miRNA that has been shown to repress tumor growth and metastasis, shares identical seed sequences and target genes with miR-449a, such as SATB2, Sirt1 and HDAC1." (PMID 29254139, 2017). "SIRT1 protein is a positive regulator of EMT and tumor metastasis." (PMID 27935857, 2017). "In the annual fish, resveratrol down-regulated acetylation of K-Ras, phosphorylation of FoxO3a, acetylation of FoxO1 and phosphorylation of DLC1 by SIRT1 or SIRT1-mediated inactivation of K-Ras/PI3K/AKT signal, and inhibited cell proliferation and promoted cell apoptosis in spontaneous neoplasms." (PMID 28903430, 2017). "Apoptosis induced by resveratrol might be resulted from deacetylation and dephosphorylation of FoxOs, up-regulation of DLC1 and interaction between SIRT1 and DLC1, and dephosphorylation of DLC1 in spontaneous neoplasms of the fish." (PMID 28903430, 2017). "Considering the diverse targets of SIRT1, it is not surprising that SIRT1 can act as a tumor promoter or suppressor depending on cell context." (PMID 26992208, 2016). "The exact role of sirtuins in cancer remains controversial with dichotomous functions being reported, for example multiple studies have shown that SIRT1, SIRT3 and SIRT5 can act as tumor promoters or tumor suppressors under different cellular conditions, tumor stage and tissue of origin." (PMID 27465020, 2016). "Therefore, next, we performed co-immunoprecipitation assays to examine the interaction of Sirt1 and NF-κB in CRC cells in alginate tumor microenvironment cultures." (PMID 26959057, 2016).
tumor (continued). "miR-22 acts as a tumor suppressor and induces cellular senescence by regulating cyclin-dependent kinase inhibitor 1A (CDKN1A), cyclin-dependent kinase 6 (CDK6), sirtuin 1 (SIRT1), and specificity protein 1 (Sp1)." (PMID 26927063, 2016). "As tumor size, rather than tumor frequency is decreased in this genetic background, SIRT1 likely influences post-initiation events in this system." (PMID 26882112, 2016). "As with SIRT1, SIRT6 plays both tumor suppressing and promoting roles." (PMID 27916001, 2016). "We suggest that this confusion arises from the fact that SIRT1 has not been explored based on the concept of tumor-stroma interplay." (PMID 26992208, 2016). "In contrast, in 18 of 33 samples (54.5%) adjacent tumour tissues did not express SIRT1, and only 4 samples (12.1%) showed obvious SIRT1 expression." (PMID 27793039, 2016). "In contrast, transfection with Sirt1-ASO significantly inhibited resveratrol-induced upregulation of Sirt1 expression in both CRC cell lines, indicating that Sirt1 is one of the main target proteins by resveratrol during the resveratrol-anti-tumor effect in CRC cells." (PMID 26959057, 2016). "Tumor latency was reduced in animals fed a high fat diet but this effect was not dependent on SIRT1 activity." (PMID 25380034, 2014). "The kappa coefficients for scoring of the tumor tissues were 0.664 for LSD1 and 0.627 for SIRT1." (PMID 25139823, 2014). "Treatment with resveratrol did not affect tumor latency in either Sirt1+/+ or Sirt1Y/Y mice nor did resveratrol have an evident effect on survival duration." (PMID 25380034, 2014). "High expression of all three enzymes in tumor cells was correlated with reduced patient survival and shortened RFS compared to the expression level of the individual enzymes, implicating that LSD1, HDAC2 and SIRT1 act together in the same complex." (PMID 25139823, 2014). "Overall, 51 (53.7%) of the 95 SIRT1-positive patients and 24 (21.6%) of the 111 SIRT1-negative patients suffered tumor relapse (P < 0.001, chi-square test)." (PMID 25922660, 2014). "In this study, we found that SIRT1 expression was high in most primary HCC tumor tissues compared with that in corresponding non-tumorous liver tissues by immunohistochemical analysis." (PMID 25522783, 2014). "The results confirmed the overexpression of SIRT1 in ESCC tumor tissues when compared with paired nontumorous tissues." (PMID 25922660, 2014). "SIRT1 also has a role in tumour suppression in non-transformed cells via maintenance of genomic stability." (PMID 24258275, 2013). "Tumor development in mice with catalytically inactive SIRT1(H355Y) protein was not accelerated, a result inconsistent with the notion that Sirt1 is a tumor suppressor." (PMID 24278473, 2013). "Tumors that arise in MMTV-PyMT mice metastasize to the lung and this late stage of tumor progression is also not accelerated in Sirt1Y/Y mice suggesting that SIRT1 has little effect at even late stages of tumor development." (PMID 24278473, 2013). "Secondly, we did not yet explore the molecular mechanism under which SIRT1 regulated the cell biological behaviors and its influence on chemosensitivity to anti-tumor medications." (PMID 24223900, 2013).
tumor (continued). "SIRT1 inhibits the acetylated form of N1IC and significantly diminishes N1IC activity induced by p300, thereby limiting the DLL4/Notch signaling response and inhibiting tumor angiogenesis." (PMID 23028940, 2012). "Furthermore, our results demonstrate that miR-34a can also regulate tumor angiogenesis by directly inhibiting angiogenic functions of endothelial cells by downregulating a number of key proteins including E2F3, SIRT1, survivin and CDK4." (PMID 22629428, 2012). "Specifically, tumor cells demonstrated stronger expression of c-Myc and SIRT1 than adjacent non-transformed hepatocytes." (PMID 23024800, 2012). "Based on the findings that SIRT1 and SIRT4 transcripts show dynamic responses to induction of differentiation, SSL, and oxidative stress, we examined the expression of SIRTs in human normal, premalignant (AK), and tumor (SCC) skin biopsies." (PMID 22860104, 2012). "Moreover, the SIRT1 inhibitors reactivate MKP3 gene expression in tumor and pre-cancerous cells, reduce N-Myc protein expression, inhibit N-Myc-induced tumor initiation and progression in vivo." (PMID 21698133, 2011). "SIRT1 is localized to the promoters of these methylated and silenced tumor suppressor genes, but not to promoters of the same genes in cell lines where they are normally maintained in an unmethylated, open chromatin state facilitating gene expression." (PMID 18704159, 2008). "For HDACs with a broader deacetylation specificity than SIRT1, such as HDAC1 and HDAC2, no somatic mutations in tumours have been described, but a dysregulated expression seems to be a common feature of human neoplasia." (PMID 16404435, 2006). "Additionally, kallistatin may antagonize endothelial nitric oxide synthase (eNOS), sirtuin 1 (SIRT1) and microRNA (miRNAs)-mediated inflammation, oxidative stress and tumor growth via its active site." (PMID 41561118, 2025). "One study described that SIRT1 was significantly overexpressed in type I EC compared to normal endometrial tissue, and this overexpression correlates with improved progression-free survival, suggesting a potential tumor-suppressive role in this subtype." (PMID 41300302, 2025). "In tumor-bearing mice, Lipopolysaccharide-induced tumor necrosis factor alpha factor (LITAF) acts as a tumor suppressor gene, promoting FOXO-1 expression to inhibit SIRT1, thereby upregulating epithelial marker E-cadherin and downregulating mesenchymal marker N-cadherin." (PMID 40567502, 2025). "Moreover, the upregulation of SIRT1 and CX3CL1 was significantly correlated with several aggressive clinicopathological features of CRC, including advanced tumor stage, increased lymphatic and distant metastasis rates, and increased tumor invasion depth." (PMID 39783838, 2025). "Ubiquitination (via SCF-FBXW7, RNF20, RNF139) or deacetylation (via SIRT1) promotes SREBP1 degradation, inhibiting fatty acid metabolism and maintaining lipid homeostasis. mTORC1 activation and SREBP1 acetylation enhance its stability and promote lipid metabolism, supporting tumor growth." (PMID 40370434, 2025). "In addition, it may also exert tumor-promoting effects through the NAD+ salvage pathway and SIRT1 activation." (PMID 39940750, 2025). "In summary, we believe that the dual function of SIRT1 in CRC is due to its regulation by different upstream molecules in different stages of CRC, as well as the main target pathways in the occurrence and progression of CRC, and more importantly, the influence of tumor microenvironment." (PMID 40229278, 2025).
tumor (continued). "Additionally, we demonstrate that Sirt1 plays a vital role in suppressing the transcriptional activity of FOXO1 through deacetylation, leading to decreased androgen secretion and ultimately suppressing tumor progression in GBM." (PMID 40075208, 2025). "Moreover, SIRT1 expression positively correlates with β-Catenin and ARID1A, both known tumor suppressors, which may contribute to the favorable prognosis observed in patients with higher SIRT1 levels." (PMID 41300302, 2025). "Overexpression of SIRT1 enhanced FOXO3 deacetylation and activity, promoting BNIP3 transcription and PINK1/Parkin-mediated mitophagy, which in turn promoted cell proliferation, migration, invasion, and inhibited apoptosis in vitro, as well as increased tumor growth and hormone resistance in vivo." (PMID 39266959, 2024). "Therefore, reports on increased SIRT1 levels in CRC through tumour progression, for example 53, do not demonstrate that SIRT1 deacetylase activity also increases, especially in the presence of Wnt signalling, which we show that inactivates SIRT1." (PMID 39494323, 2024). "This is also important to interpret the correlation between SIRT1 overexpression or depletion and tumour size in xenografts 53, since increased SIRT1 levels may not correlate with increased SIRT1 deacetylase activity." (PMID 39494323, 2024). "Notably, we found that the protein and mRNA expression levels of SIRT1 were aberrantly increased in NSCLC cells harboring KRASMut and in KRASG12D mouse lung tumors compared with normal lung epithelial cells and with tumor-adjacent normal tissues and KrasWT mouse lung tissues, respectively." (PMID 37779142, 2023). "After immunotherapy (After Tumor), the activated pathways in the tumor were mainly related to epigenetic modification such as RMTs methylate histone arginine, HDAC deacetylate histones, PRC2 methylates histones and DNA, SIRT1 negatively regulating rRNA expression, and DNA methylation." (PMID 38136558, 2023). "Global acetylation also showed high cellular intratumor heterogeneity and variability between samples without statistically significant differences between tumor and nontumor samples (data not shown), showing that is not a valid, specific read out of SIRT1 activity." (PMID 37530744, 2023). "Notably, the combination of SIRT1-knockdown with the DDP treatment elicited a more pronounced diminishment in both the tumor volume and weight, accompanied by a further increase in the apoptosis rate of the tumor cells." (PMID 38201552, 2023). "Furthermore, a recent study showed that globular adiponectin induces tumor suppression by decreasing the cellular lipid pool, mainly through the inhibition of fatty acid synthase (FAS) and the activation of Sirtuin 1 (SIRT-1), which will promote apoptosis in vivo and in vitro." (PMID 36428526, 2022). "However, it is thought that AROS is a weak activator of SIRT1, and that this form of activation is relatively non-existent in tumor cells." (PMID 35359990, 2022). "Furthermore, the increased expression of NAMPT by influencing Sirt-1, vascular endothelial growth factor (VEGF), and matrix metalloproteinase (MMP) activity significantly stimulates angiogenesis and thus contributes to the progression of tumor development." (PMID 36233428, 2022). "Moreover, virus-mediated overexpression of miR-199 and miR-34a has been found to lead to control of tumor growth by targeting mTOR, c-MET, HIF-1α, and CD44, as well as complete tumor regression by targeting Bcl-2 and SIRT1 in xenograft murine models of HCC, respectively." (PMID 35954176, 2022). "In addition to SIRT1, SIRT2 functions in a binary manner, as a tumor suppressor or promoter." (PMID 36581622, 2022). "SIRT1 is expressed in the cytoplasm and nucleus in liver tissues, and its expression levels increased in metastatic 4TLM and non-metastatic 67NR liver tissues compared to tumor-free liver tissue (p ˂ 0.05)." (PMID 36142156, 2022).